CXCR5 (C-X-C motif chemokine receptor 5)
Diseases named in the same sentence as CXCR5 in open-access papers (continued):
Sharing a sentence is not in itself a finding about the gene and the disease.
lymphoma (continued). "To assess the cytotoxic potential of TFK cells, we performed a killing assay using FACS-sorted CD19+ B cells (predominantly malignant lymphoma cells) and co-cultured with either CD4+PD-1+CXCR5+TIA-1– TFH or CD4+PD-1+CXCR5+TIA-1+ TFK FACS-sorted from FL and DLBCL samples." (PMID 41030456, 2025). "Although significantly lower levels of CD20+CD27+CD24+CD40+CXCR4+CXCR5+ B cells were observed in MC14 of HIV+ pre-NHL (cART-naïve) samples, these cells had a potential pre-lymphoma phenotype as they expressed both cMYC and AICDA compared to HIV+ cART-naïve and HIV-negative samples." (PMID 39324141, 2024). "Interestingly, we did not observe any substantial differences between GC-B and the lymphoma entities for the B-cell homeostatic chemokine receptors, CXCR3, CXCR4, and CXCR5." (PMID 35887224, 2022). "CXCR5 was expressed by PVRL as well as PCNSL and PTL lymphoma cells." (PMID 36233057, 2022). "We compared the eyes of a lymphoma PDX model derived from a PCNSL versus SCNSL patient stereotactic CNS biopsy regarding infiltration of human CD20 positive lymphoma cells and immunohistochemical expression of the homing receptors CXCR4, CXCR5, CXCR7 and CD44." (PMID 36233057, 2022). "We hypothesized that CXCR4, CXCR5, CXCR7 and CD44 are expressed on CD20-positive lymphoma cells in the eyes of this PCNSL PDX model." (PMID 36233057, 2022). "Differences in the homogeneity and height of CXCR5 and CD19 expression on the primary lymphoma cells may play a role in this observation." (PMID 33431832, 2021). "Next, we assessed whether the CXCR5 CAR also mediates the superior killing of FL, CLL, and MCL lymphoma cells in comparison to the CD19 CAR." (PMID 33431832, 2021). "Specific chemokine receptors and adhesion molecules make lymphoma cells capable of “homing in” on certain body sites (e.g., lymph nodes for CCR7 and CXCR4/CXCR5) and this property might be the basis of primary disseminated clinical presentation of lymphoma." (PMID 31947775, 2020). "CXCR5 and/or CXCL13 expression is elevated in certain carcinomas and lymphomas." (PMID 25271023, 2014). "Second, these results are consistent with our previously published results that most primary human AIDS-lymphomas, including tumors of the Burkitt subtype, were positive for both CXCR5 and CXCL13 expression, and that serum levels of CXCL13 were elevated in subjects who developed AIDS-lymphoma." (PMID 23936541, 2013). "The CXCR5 gene is expressed regularly and strongly in lymphomas of mature B cells but not in plasmacytomas." (PMID 20504365, 2010). "One next step will be to clone the TCRs from the expanded TFK clones and determine their antigen specificity, i.e. whether they are engaged by lymphoma-derived peptides or whether CXCR5+ TFK cells, which naturally home to the atypical follicles, should be equipped with a lymphoma-recognizing CAR." (PMID 41030456, 2025). "The CD20+CXCR4hiCD24+CXCR5+CD40+CD4+ B-cell population in MC23 of HIV+ pre-NHL (cART-naïve) samples displayed a mature and activated phenotype (IgM+HLADR+) with a potential pre-lymphoma feature as it expressed AICDA compared to MC23 of HIV+ cART-naïve samples." (PMID 39324141, 2024). "However, expression of the exhaustion markers PD-1, LAG-3, and TIM-3 were not upregulated on CXCR5 CAR-T compared to SP6 CAR-T cells when we analyzed the persistence of CXCR5 CAR T cells in vivo at the time of lymphoma cell outgrowth." (PMID 33431832, 2021). "Both lymphomas contained significantly more FOXP3+ Tregs, which was reflected in more CD4+FOXP3+CXCR5+PD-1+ TFR cells among CD4+ T cells, but not among Tregs for FL." (PMID 41030456, 2025). "The immunohistochemistry with tumor tissue showed the positive staining for CXCR5 and negative for CXCL13 on lymphoma cells." (PMID 25966773, 2015).
prostate carcinoma (21 papers, 2013 to 2025). A carcinoma that arises from epithelial cells of the prostate gland. "While CXCR4 is present in almost all invasive cancers, CXCR5 has been implicated in advanced stages of chronic myelogenous leukemia, head and neck cancers, colon, and prostate cancer." (PMID 23773523, 2013). "The CXCL13/CXCR5 axis promotes the proliferation and invasion of prostate cancer (PCa) cells by activating JNK, ERK, SRC/FAK, PI3K, and Akt." (PMID 34947813, 2021). "Recent studies reported that CXCR5 was overexpressed and associated with PNI in colorectal and prostate cancers." (PMID 34114971, 2021). "In this context, CXCL13 and CXCR5 appear to be highly relevant in prostate cancer cell proliferation, migration, and invasion, ultimately impacting disease progression and metastatic dissemination." (PMID 31354634, 2019). "The gene ontology results further imply CXCL13 and CXCR5’s role in the development of prostate cancer." (PMID 31628349, 2019). "In normal tissue and benign prostate hyperplasia samples, CXCR5 displays a predominant membrane and/or cytoplasmic distribution while in advanced prostate cancers it shows high nuclear expression." (PMID 31354634, 2019). "Recent discoveries linking up-regulation of the CXCL13:CXCR5 axis to the dissemination of prostate cancer stem-like cells to lymph nodes and bone marrow further support this concept." (PMID 31354634, 2019). "Early studies showed that CXCR5 is expressed in primary prostate cancer tissues at higher levels than normal tissue." (PMID 31354634, 2019). "Inhibition of CXCL13 or CXCR5 can impair the migratory and tumorigenic properties of prostate cancer cells." (PMID 30723697, 2018). "Recently, the overexpression of CXCR5 in breast and prostate cancer patients was found to be highly correlated with lymph node metastasis and infiltration." (PMID 29377892, 2018). "Prostate cancer (PCa) cell lines and tissues differentially express CXCR5, which positively correlate with PCa progression, and mediate PCa cell migration and invasion following interaction with CXCL13." (PMID 23773523, 2013). "CXCR5/CXCL13 is related to bone metastasis of prostate cancer." (PMID 41333471, 2025). "Silica nanoparticles loaded with snake venom may cause apoptosis and limit proliferation in human prostate cancer cells, as well as dramatically lower the levels of numerous chemokines (including CXCL13) and their receptors (including CXCR5)." (PMID 34922542, 2021). "Furthermore, CXCL13 produced by bone marrow endothelial cells in response to IL-6 was able to induce prostate cancer cell invasion in a CXCR5-dependent manner." (PMID 31354634, 2019). "Indeed, silencing CXCR5 from prostate cancer cells reduces their proliferative, tumorigenic and motile capacities." (PMID 31354634, 2019). "Furthermore, it is reported that the CXCR5–CXCL13 axis could promote the progression of ccRCC, and overexpression of CXCR5 facilitated tumor cell proliferation through JNK pathway in prostate cancer." (PMID 33324682, 2020). "CXCL13-dependent cell invasion in prostate cancer (PCa) cells was significantly inhibited by the application of siRNA targeting Gαq and Gαi2, indicating that the CXCL13/CXCR5/Gαq signaling pathway regulates cellular chemotaxis." (PMID 35053457, 2022). "In accordance with Haibi et al44 reported in prostate cancer, CXCL13/CXCR5‐promoted cell migration and invasion was regulated by Src activation." (PMID 34427969, 2021). "Both CXCR5 and CXCR4 are involved in metastasis of PCSLC prostate cancer stem-like cells, and inhibition of CXCR4 alters the homing of quiescent stem-like prostate cancer cells to bone." (PMID 30873179, 2019). "It is reported that CXCL13/CXCR5 axis promoted colon cancer growth and invasion via PI3K/AKT pathway, mediated prostate cancer cell proliferation through JNK and ERK signaling." (PMID 30723697, 2018). "In prostate cancer, CXCL13 mediates MMPs expression and actives protein secretion in a CXCR5-dependent way." (PMID 30723697, 2018).
prostate carcinoma (continued). "Expression of CXCR5, a corresponding receptor for CXCL13, was higher in prostate cancer cases, and the intensity of CXCR5 expression positively correlated with the Gleason score." (PMID 25912035, 2015). "Altogether, evidence indicates that a complex network of cellular interactions involving CXCL13 and CXCR5 integrate to promote prostate cancer cell autonomous and non-autonomous pathways." (PMID 31354634, 2019). "Depending on PI3Kp110, Src and FAK, the interaction of CXCR5 with its specific ligand—CXCL13, could promote prostate cancer cell invasion, migration, and differential matrix metalloproteinase (MMP) expression." (PMID 25990390, 2015).
Sjögren’s syndrome (21 papers, 2008 to 2025). "As CXCR5+CCR6+ TFH cells may participate in the antibody‐associated immune responses in Sjögren's syndrome, our results indicate the involvement of this TFH subset in SL‐induced immune dysregulation." (PMID 37132178, 2023). "In Sjögren’s syndrome, CXCR5 is involved in the formation of germinal centers and lymphocyte migration." (PMID 40321894, 2025). "The ICOS+PD-1+ cTfh cells and IL-21 producing CD4+CXCR5+PD-1+ T cells were also shown to be significantly higher in patients with Sjögren syndrome." (PMID 33465845, 2021). "Viewed together, these observations suggest the tissues of Sjogren's syndrome patients and NOD mice accumulate IL-21-producing B cell-helper T cell populations that can lack typical Tfh-associated features such as Bcl6 and CXCR5." (PMID 30190721, 2018). "However, in Sjögren’s Syndrome, a chemokine receptor called CXCR5 directs B-cell migration to germinal centers in secondary lymphoid organs, promoting long-term immunological activation." (PMID 40321894, 2025). "Mucosal-associated invariant T (MAIT) cells might play a role in B cell hyperactivity and local inflammation in primary Sjögren’s syndrome (pSS), just like previously studied mucosa-associated CCR9+ and CXCR5+ T helper cells." (PMID 36505431, 2022). "In Sjogren's syndrome patients, CCR9+ CXCR5− T cells from the blood produced CXCL13 (in addition to IL-21 ), albeit at lower levels than was produced by CXCR5+ cells." (PMID 30190721, 2018). "Increased numbers of human peripheral blood CXCR5+ICOS+, CXCR5+PD-1+ Tfh cells and enhanced GC formation positively correlate with autoantibodies titers and severity of the primary Sjögren’s syndrome (pSS)." (PMID 30158933, 2018). "Even though cells defined in this way best resemble activated Tfh cells found in lymphoid structures, in some studies—including those studying Sjögren’s syndrome—(memory) CXCR5+ CD4 T cells without extensive further phenotyping are pragmatically also considered Tfh cells." (PMID 37569326, 2023).
lung carcinoma (19 papers, 2014 to 2024). "Anti-tumor activity of the CXCL13/CXCR5 axis has also been reported, which is shown to be able to promote the formation of TLSs and is linked to improved survival of lung cancer patients." (PMID 34947813, 2021). "Deficiency in Cxcl13 or its receptor, Cxcr5, significantly attenuated BaP-induced lung cancer in mice, demonstrating CXCL13’s critical role in PAH-induced lung carcinogenesis." (PMID 26565418, 2015). "We found that CXCL13 was a direct target of AhR, and deficiency in CXCL13 or its receptor, CXCR5, abrogated BaP-induced lung cancer, while an anti-CXCR5 antibody significantly inhibited lung cancer cell migration." (PMID 26565418, 2015). "Also, CXCL13/CXCR5 axis contributed to cell motility in lung cancer cells, which was caused by VCAM‐1 expression." (PMID 34427969, 2021). "Interestingly, deficiency in CXCL13 or CXCR5 significantly inhibits BaP-induced lung cancer in mice, indicating the critical role of this axis in environmental lung carcinogenesis." (PMID 34947813, 2021). "CXCR5, also known as Burkitt's lymphoma receptor 1, is abnormally increased in a variety of tumors such as gastric cancer, breast cancer, intestinal cancer, prostate cancer, malignant neuroblastoma, and lung cancer, and it is significantly associated with poor prognosis." (PMID 33829065, 2021). "Because DEX is a wide-spectrum anti-inflammatory drug that may cause severe side effects, more specific, CXCL13/CXCR5-targeting antibodies or small molecules should be developed to combat lung cancer, the leading cause of cancer-related mortality accounting for 1.59 million deaths worldwide in 2012." (PMID 26565418, 2015). "A few reports regarding breast and lung cancers have shown that the CXCL13/CXCR5 axis attracts B cells to form TLSs at peritumoral or tumor sites." (PMID 39611128, 2024). "BaP-induced lung tumors in mice displayed increased CXCL13 levels, while CXCL13 or CXCR5 knockout significantly suppressed the development of Bap-induced lung cancer." (PMID 36217194, 2022). "In conclusion, our present study suggests that CXCL13/CXCR5 axis is up‐regulated in lung cancer cells, which promotes VCAM‐1 expression and further cell migration." (PMID 34427969, 2021). "In conclusion, these evidences suggest that the CXCR5, PLCβ, PKCα and c‐Src signalling pathways mediate NF‐κB activation in lung cancer cells treated with CXCL13." (PMID 34427969, 2021). "Here, we found that Src was activated by CXCL13/CXCR5 axis and subsequently regulated cell migration in lung cancer cells." (PMID 34427969, 2021). "This evidence suggests that CXCL13/CXCR5 axis activation is common feature in lung cancer progression." (PMID 34427969, 2021). "We found that expression levels of CXCL13 and CXCR5 were highly correlated with lung cancer progression." (PMID 34427969, 2021). "Based on our finding here, the clinical relevance of CXCL13/CXCR5 in lung cancer progression and development of novel therapeutic targets should be addressed in the future." (PMID 34427969, 2021). "Deficiency in CXCL13 or CXCR5 significantly suppressed BaP-induced lung cancer in mice, indicating that CXCL13 plays a key role in smohaze carcinogen-induced lung cancers." (PMID 34947813, 2021). "Here, we report the prognostic relevance of CXCL13/CXCR5 and found that they are commonly overexpressed among different subtypes of lung cancer." (PMID 34427969, 2021). "Our finding here supposes that CXCL13/CXCR5 axis is a major regulator of VCAM‐1 up‐regulation in lung cancer." (PMID 34427969, 2021). "Here, we found that expression levels of CXCL13 and CXCR5 were highly correlated with lung cancer progression." (PMID 34427969, 2021). "Our present work provides novel application of CXCL13/CXCR5 axis in lung cancer therapeutic strategy." (PMID 34427969, 2021). "In this study, we found that CXCL13 and CXCR5 were commonly up‐regulated in lung cancer specimens compared with normal tissues among different cohorts." (PMID 34427969, 2021).
lung carcinoma (continued). "CXCL13-CXCR5 signaling was required for PAH-induced lung cancer, because knockdown of Cxcl13 or Cxcr5 attenuated BaP-induced lung cancer in mice." (PMID 26565418, 2015). "Our findings demonstrate that CXCR5 is differentially expressed in lung carcinomas depending on stage of the disease." (PMID 25271023, 2014). "The CXCL13 : CXCR5 axis might be involved in the promotion of lung cancer, and the B cell chemoattractant chemokine (CXCL13) is elevated in NSCLC patients, suggesting that it could be used as a predictor of the risk of early-stage lung adenocarcinoma." (PMID 36164329, 2022). "In regard to the key role of Src in tumour progression, combination therapy of CXCL13/CXCR5 axis and Src inhibitors may provide clinical benefits in lung cancer treatment." (PMID 34427969, 2021). "Our present work reveals that CXCL13/CXCR5 axis could be a novel therapeutic target against lung cancer." (PMID 34427969, 2021). "A few reports regarding breast and lung cancers have shown that the CXC13/CXCR5 axis attracts B cells and Tfh to shape the TLS in the peritumoral or tumor sites, which is associated with adaptive anti-tumor humoral responses and predicting responses to PD-1 blockade therapy." (PMID 34947813, 2021). "We found that the CXCR5 was expressed in B cells from both PBMCs and lung cancer." (PMID 35069521, 2021). "However, the prognostic value and pathological role of CXCL13/CXCR5 in lung cancer is still in its infancy." (PMID 34427969, 2021). "We showed that BaP treatment induced lung cancer in Cxcr5+/+ mice." (PMID 26565418, 2015). "Therefore, we hypothesized that CXCL13‐induced lung cancer cell migration may be regulated by CXCR5." (PMID 34427969, 2021). "On the other hand, CXCL13 recruits CXCR5+ CD68+ macrophages secreting SPP1, which triggers tumor cell migration through the EMT pathway in lung cancer." (PMID 34947813, 2021). "Meanwhile, CXCR5 neutralized antibody also dose‐dependently reversed cell migration and VCAM‐1 expression in CXCL13‐treated lung cancer cells." (PMID 34427969, 2021). "Previous report showed that high levels of CXCR5 and CXCL13 were up‐regulated in tissues and sera of lung cancer patients respectively." (PMID 34427969, 2021). "The relevance of CXCL13 in Ba[a]P-induced lung cancer was further confirmed using CXCL13 and CXCR5 knockout mice, which have impaired tumor formation in response to the carcinogen." (PMID 31354634, 2019). "Reports from our and other labs have shown nuclear localization of CXCR5 and CXCR4 in prostate and, breast and lung cancer respectively." (PMID 25888629, 2015). "Surprisingly, with meta‐analysis in all lung cancer tissues containing adenocarcinoma (LUAD) and squamous‐cell carcinoma (LUSC), we found consistent up‐regulation of CXCL13 and CXCR5 in multiple lung cancer studies, suggesting the impact of CXCL13‐CXCR5 axis in lung cancer progression." (PMID 34427969, 2021). "Multiple reports using flow cytometry and single‐cell sequencing on solid tumors show the presence of memory‐like T cells among tumor infiltrating lymphocytes (TILs) with similarities to CXCR5+PD‐1+ CD8 T cells in melanoma, lung cancer, pancreatic cancer, and colon cancer." (PMID 33098668, 2021). "Some studies have also revealed the roles of CXCR4, CXCR5 and CCR7 in lung cancer." (PMID 32896997, 2020).